OR1S2 (olfactory receptor family 1 subfamily S member 2)
Description:
Odorant receptor.
Synonyms: OR11-231
Gene: Protein-coding gene on chromosome 11 (58,203,204 to 58,204,142, reverse strand). Ensembl gene ENSG00000197887.
Subcellular location: Cell membrane
Pathways (Reactome):
Sensory Perception: Expression and translocation of olfactory receptors
Genetic constraint (gnomAD): Loss-of-function variants: 4 observed, 5.31 expected, observed/expected ratio (o/e) 0.75, 90% interval 0.37 to 1.63. That is too few expected variants to judge how well the gene tolerates losing a copy. Missense variants: 391 observed, 377.09 expected, observed/expected ratio (o/e) 1.04, 90% interval 0.95 to 1.13. Synonymous variants: 157 observed, 142.07 expected, observed/expected ratio (o/e) 1.11, 90% interval 0.97 to 1.26.
Homologues: Orthologues: macaque OR1S1 (91% identical), mouse Or1s2 (80% identical), rat Or1s2 (76% identical). Paralogues in human: OR1S1 (92% identical), OR1F1 (54% identical), OR1M1 (53% identical), OR7C2 (53% identical), OR1J4 (53% identical), OR1N2 (52% identical), OR7D4 (52% identical), OR1J2 (52% identical), OR1N1 (52% identical), OR1I1 (51% identical), OR1P1 (51% identical), OR7C1 (51% identical), and 116 more.